NDUFA11 (NADH:ubiquinone oxidoreductase subunit A11)
Description:
Accessory subunit of the mitochondrial membrane respiratory chain NADH dehydrogenase (Complex I), that is believed not to be involved in catalysis. Complex I functions in the transfer of electrons from NADH to the respiratory chain. The immediate electron acceptor for the enzyme is believed to be ubiquinone.
Synonyms: CI-B14.7; B14.7; MC1DN14
Tractability: Small molecule: an approved drug acts on it; a structure with a bound ligand is known. Antibody: UniProt predicts a signal peptide or a membrane-spanning region. PROTAC: ubiquitination databases record sites on it; its protein half-life has been measured.
Gene: Protein-coding gene on chromosome 19 (5,891,207 to 5,904,006, reverse strand). Ensembl gene ENSG00000174886.
Subcellular location: Mitochondrion inner membrane
Subcellular location (Human Protein Atlas): End piece; Mitochondria; Perinuclear theca; Principal piece
Pathways (Reactome):
Metabolism: Complex I biogenesis; Respiratory electron transport
Gene Ontology:
Molecular function: protein binding
Biological process: aerobic respiration; proton motive force-driven mitochondrial ATP synthesis; mitochondrial electron transport, NADH to ubiquinone
Cellular component: mitochondrial inner membrane; mitochondrion; respiratory chain complex I
Genetic constraint (gnomAD): Loss-of-function variants: 14 observed, 11.96 expected, observed/expected ratio (o/e) 1.17, 90% interval 0.77 to 1.76. The upper end of that interval is the gene's LOEUF score, 1.76, which puts it in group 6 of 6, group 1 being the genes least tolerant of losing a copy. Missense variants: 204 observed, 180.6 expected, observed/expected ratio (o/e) 1.13, 90% interval 1.01 to 1.27. Synonymous variants: 87 observed, 79.22 expected, observed/expected ratio (o/e) 1.1, 90% interval 0.92 to 1.31.
Gene-disease validity (ClinGen):
ClinGen rates the evidence that NDUFA11 causes each of these diseases.
mitochondrial disease (autosomal recessive): Limited.
Homologues: Orthologues: chimpanzee NDUFA11 (76% identical), macaque NDUFA11 (73% identical), dog NDUFA11 (72% identical), pig NDUFA11 (70% identical), guinea pig NDUFA11 (69% identical), rat Ndufa11 (67% identical), mouse Ndufa11 (65% identical), rabbit NDUFA11 (59% identical), tropical clawed frog ndufa11 (48% identical), zebrafish ndufa11 (47% identical), Drosophila melanogaster ND-B14.7 (31% identical).
Diseases named in the same sentence as NDUFA11 in open-access papers:
NDUFA11 is named in the same sentence as 27 diseases in open-access papers, as found by Europe PMC text mining. Sharing a sentence is not in itself a finding about the gene and the disease. The quoted sentences say what the papers report.
bladder cancer (3 papers, 2024 to 2025). "It has also been suggested in the literature that NDUFA11 may be a potential therapeutic target in bladder cancer." (PMID 40002900, 2025). "NDUFA11 is also confirmed as a factor with high risk for predicting OS of patients with bladder cancer and has a negative correlation with the prognosis of patients with bladder cancer." (PMID 41364140, 2025).
breast carcinoma (3 papers, 2021 to 2024). "Studies have proven that silencing of NDUFA11 inhibits superoxide and ROS production in breast cancer cells." (PMID 38649690, 2024). "We also found that the expression of RORα negatively correlated with NDUFS6 and NDUFA11 mRNA levels in human breast cancer tissue (TCGA breast cancer dataset)." (PMID 34639006, 2021). "We showed that silencing NDUFS6 and NDUFA11 suppressed superoxide and ROS generation in breast cancer cells." (PMID 34639006, 2021). "The negative correlation between RORα expression and mRNA levels of NDUFS6 and NDUFA11 suggests that these two genes are the major targets of RORα mediating its function in ROS regulation during breast cancer progression." (PMID 34639006, 2021). "We also found that silencing NDUFS6 and NDUFA11 increased OCR in breast cancer cells." (PMID 34639006, 2021). "In addition, the upregulation of complex I subunits in RORα-silenced mammary epithelial cells was accompanied by reduced OCR, while silencing NDUFS6 and NDUFA11 increased OCR in breast cancer cells." (PMID 34639006, 2021).
cervical cancer (3 papers, 2021 to 2025). A primary or metastatic malignant neoplasm involving the cervix. "Overexpression of AKR1C2 is found to be a mildly favorable prognostic marker but lower expression of NADH:ubiquinone oxidoreductase subunit A11 (NDUFA11) is prognostically unfavorable in cervical cancer." (PMID 34790674, 2021).
COVID-19 (2 papers, 2023). A disease caused by infection with severe acute respiratory syndrome coronavirus 2. "Genes impacting mitochondrial function include 31 of 37 in mitochondrial DNA and nuclear genes encoding mitochondrial proteins, including ten EDS-related (NDUFA-11/S3, OPA1, TYMP, etc.)and three COVID-19-related (STAT2, TLR3, NDUFAF7) genes." (PMID 37504295, 2023). "However, under reduced oxygen saturation in the lung of COVID-19 patients, downregulation of genes encoding lipid uptake, FAO, and NADH oxidation (NDUFB8, NDUFA11, NDUFA13) was found in severe COVID(+) NKTs suggesting mitochondrial dysfunction in NKTs during SARS-CoV-2 infection." (PMID 37029220, 2023).
glioma (2 papers, 2023 to 2025). A benign or malignant brain and spinal cord tumor that arises from glial cells (astrocytes, oligodendrocytes, ependymal cells). "In our evaluation of the risk factors of eight genes, we identified SLC3A2, RPN1, NDUFA11, GYS1 and OXSM as potential risk factors for glioma prognosis." (PMID 38022537, 2023). "The forest map shows that these five genes (SLC3A2, RPN1, NDUFA11, GYS1, OXSM) might be high-risk factors for glioma prognosis." (PMID 38022537, 2023). "GYS1, NDUFA11, OXSM, RPN1, and SLC3A2 play a role in promoting cancer in glioma, while LRPPRC, NCKAP1, NDUFS1, NUBPL and SLC7A11 play a role in inhibiting tumour." (PMID 39993959, 2025). "In glioma, RPN1, NDUFA11, and GYS1 were significantly positively correlated with StromalScore, ImmuneScore, and ESTIMATEScore." (PMID 38022537, 2023).
acute myocardial infarction (1 paper, 2025). Necrosis of the myocardium, as a result of interruption of the blood supply to the area. "Additionally, other studies have shown that NDUFA11 expression was significantly reduced in the blood of patients with acute myocardial infarction, making it a potential biomarker for diagnosis of myocardial infarction." (PMID 40344088, 2025).
bladder urothelial carcinoma (1 paper, 2024). "In addition, a group of disulfidptosis-related genes (GYS1, LRPPRC, NDUFA11, OXSM, RPN1, SLC3A2, and SLC7A1) are found to influence the prognosis of bladder urothelial carcinoma via immune cell infiltration." (PMID 39701955, 2024).
Brain atrophy (1 paper, 2020). Partial or complete wasting (loss) of brain tissue that was once present. "Mutations in NDUFA11 cause severe neurodegenerative phenotypes such as brain atrophy and encephalopathy, and mutations in TKT cause diseases associated with neurological phenotypes." (PMID 32004313, 2020).
cervical squamous cell carcinoma (1 paper, 2025). A squamous cell carcinoma arising from the cervical epithelium. "Notably, NDUFA11 and BRK1 showed significant associations with patient survival, highlighting their prognostic importance in cervical squamous cell carcinoma." (PMID 40305445, 2025). "Among the four identified hub genes, NDUFA11 and BRK1 exhibited significant variations in patient survival, impacting the prognostic outcomes of patients with cervical squamous cell carcinoma (CESC)." (PMID 40305445, 2025).
diffuse large B-cell lymphoma (1 paper, 2025). "NDUFA11, as a Disulfidptosis gene, plays a role in the prognosis of diffuse large B-cell lymphoma (DLBCL)." (PMID 40002900, 2025).
lung adenocarcinoma (1 paper, 2024). A carcinoma that arises from the lung and is characterized by the presence of malignant glandular epithelial cells. "Notably, with the exception of NDUFA11, all disulfidptosis-related molecules showed differential expression in both ccRCC and lung adenocarcinoma." (PMID 38271056, 2024).
metabolic syndrome (1 paper, 2021). A cluster of metabolic risk factors for CARDIOVASCULAR DISEASES and TYPE 2 DIABETES MELLITUS. "Specifically, we identified an increased expression of the miR-224 targets Ndufa11, Cox17, Cox16b1, and Id3 in BAT, which associate with metabolic syndrome and obesity." (PMID 34342596, 2021).
prostate carcinoma (1 paper, 2025). A carcinoma that arises from epithelial cells of the prostate gland. "Among them, SLC7A11, OXSM, RPN1, and NDUFA11 showed higher expression levels in prostate cancer tissues compared to normal samples." (PMID 41330917, 2025). "Building on our previous research, further analysis of tumor progression within the training set revealed that RPN1 may act as a suppressor of prostate cancer progression, while OXSM, NDUFA11, and SLC7A11 appear to promote disease progression." (PMID 41330917, 2025).
ZIKV infection (1 paper, 2017). "Further examination of the roles of metabolic control genes such as TERT, ALDH7A1, CREB5, EAPP, and NDUFA11 as they relate to ZIKV infection may provide further insights into ZIKV pathogenesis." (PMID 28442752, 2017).
tumor (7 papers, 2019 to 2025). "Our findings reveal distinct chromosomal mappings and expression profiles of DRGs, notably the downregulation of NDUFA11 and upregulation of RPN1 in tumor tissues." (PMID 38549669, 2024). "Notably, expression profiling reveals a distinct downregulation of NDUFA11 in tumor tissues, in contrast to the upregulation observed for RPN1; the expression of the other genes remained statistically unaltered between normal and tumor samples." (PMID 38549669, 2024).
cancer (6 papers, 2023 to 2025). A tumor composed of atypical neoplastic, often pleomorphic cells that invade other tissues. "NDUFA11 encodes a subunit of membrane-bound mitochondrial complex I. Inhibition of complex I activity has been reported to enhance ROS production and promote cancer cell migration and invasion." (PMID 38649690, 2024). "Notably, NDUFA11, OXSM, LRPPRC, NCKAP1, RPN1, SLC3A2, and SLC7A11 were upregulated in cancer tissues, while NDUFS1 showed the opposite trend." (PMID 38213838, 2023).
mitochondrial disease (2 papers, 2020 to 2024). "NDUFA11 deficiency is associated with various diseases, including NDUFA11-deficient mitochondrial disease and atherosclerotic disease." (PMID 38887449, 2024).
neurodegenerative disease (1 paper, 2025). A disorder of the central nervous system characterized by gradual and progressive loss of neural tissue and neurologic function. "The mitochondrial dysfunction in the neurodegenerative diseases cluster (Cluster 4) comprises 95 genes, including several key mitochondrial protein genes acting as pivotal hub genes, such as Sdhb, Ndufa4, Ndufb4c, Ndufb4b, Ndufv3, Ndufa9, Ndufc1, Ndufs5, Ndufb4, Ndufa12, Ndufa11, and Ndufb1." (PMID 41294802, 2025).
NDUFA11 also shares sentences with these, for which no sentence is quoted: Alzheimer disease (2 papers); clear cell renal adenocarcinoma (1); Encephalopathy (1); ischemic stroke (1); Leigh syndrome (1); Malignant hyperthermia (1); neurological disorders (1); Obesity (1); ovarian carcinoma (1).